CARHSP1 (calcium regulated heat stable protein 1)
Description:
Binds mRNA and regulates the stability of target mRNA. Binds single-stranded DNA (in vitro).
Synonyms: CRHSP-24; CSDC1; CRHSP24
Tractability: Small molecule: it has a high-quality binding pocket. PROTAC: ubiquitination databases record sites on it; its protein half-life has been measured.
Gene: Protein-coding gene on chromosome 16 (8,852,942 to 8,870,941, reverse strand). Ensembl gene ENSG00000153048.
Subcellular location: Cytoplasm; Cytoplasm, P-body; Cytoplasmic granule
Gene Ontology:
Molecular function: mRNA 3'-UTR binding; protein binding; phosphatase binding; nucleic acid binding
Biological process: intracellular signal transduction; regulation of mRNA stability
Cellular component: cytoplasm; cytoplasmic exosome (RNase complex); cytosol; P granule; P-body
Genetic constraint (gnomAD): Loss-of-function variants: 11 observed, 10.08 expected, observed/expected ratio (o/e) 1.09, 90% interval 0.68 to 1.74. The synonymous counts are far from expectation, so gnomAD's model fits this gene poorly and the ratio says little. Missense variants: 294 observed, 176.88 expected, observed/expected ratio (o/e) 1.66, 90% interval 1.51 to 1.83. Synonymous variants: 139 observed, 72.99 expected, observed/expected ratio (o/e) 1.9, 90% interval 1.63 to 1.98.
Homologues: Orthologues: chimpanzee CARHSP1 (100% identical), macaque CARHSP1 (99% identical), mouse Carhsp1 (97% identical), rat Carhsp1 (97% identical), dog CARHSP1 (97% identical), guinea pig CARHSP1 (95% identical), pig CARHSP1 (95% identical), tropical clawed frog carhsp1 (74% identical), zebrafish carhsp1 (70% identical), Drosophila melanogaster CG9705 (45% identical). Paralogues in human: CSDC2 (63% identical).
Diseases named in the same sentence as CARHSP1 in open-access papers:
CARHSP1 is named in the same sentence as 12 diseases in open-access papers, as found by Europe PMC text mining. Sharing a sentence is not in itself a finding about the gene and the disease. The quoted sentences say what the papers report.
atherosclerosis (5 papers, 2016 to 2025). A disease characterized by the build-up of fatty material and calcium deposition in the arterial wall resulting in partial or complete occlusion of the arterial lumen. "miR-155 influences TNF-α mRNA stability by inhibiting calcium regulated heat stable protein 1 (CARHSP1), thereby modulating the inflammatory response and protecting vessels in atherosclerosis." (PMID 40051627, 2025). "Therefore, miR-155 is a key component of a negative feedback loop to prevent atherosclerosis-associated foam cell formation by repressing CARHSP1." (PMID 26899994, 2016).
glioma (2 papers, 2017 to 2020). A benign or malignant brain and spinal cord tumor that arises from glial cells (astrocytes, oligodendrocytes, ependymal cells). "The substantial presence of known glioma-associated genes in the neighborhood of FOXO1, PBX3 and CARHSP1 may indicate the additional presence of genes with currently unidentified roles in glioma." (PMID 28957313, 2017). "We find that in the PIN, both PBX3 and CARHSP1 are indirectly connected to each other (as well as several of their other neighbors in the CSD-network) through the intermediary of TRAF1, whose overexpression is also associated with the emergence of glioma." (PMID 28957313, 2017). "Furthermore, we performed an exhaustive literature search to identify whether any of FOXO1 or CARHSP1’s immediate neighbors also exhibited particular expression patterns related to glioma." (PMID 28957313, 2017).
brain tumors (1 paper, 2025). "In brain tumors, CARHSP1 was found to drive radioresistance by up-regulating inflammation signaling." (PMID 40073141, 2025).
breast carcinoma (1 paper, 2014). "MCF10A cells exhibited significantly increased expression of HSP90AA1, CARHSP1, HSPA12A and decreased expression of HSPB1, HSPBL2, HSPA6, and HSPA7 (C vs H), while the three breast cancer lines showed no significant 2-fold or greater alterations in the expression of these genes (C’ vs H’)." (PMID 24511912, 2014).
coronary atherosclerosis (1 paper, 2021). Atherosclerosis of the coronary vasculature. "MiR-155 was also reported to attenuate the formation of foam cells in coronary atherosclerosis and relieves the chronic inflammation by inhibiting calcium-regulated heat stable protein 1 (CARHSP1) and tumor necrosis factor alpha (TNF-α)." (PMID 34136547, 2021).
osteoarthritis (1 paper, 2021). A noninflammatory degenerative joint disease occurring chiefly in older persons, characterized by degeneration of the articular cartilage, hypertrophy of bone at the margins and changes in the synovial membrane. "Among them, Ribosomal proteins were upregulated in the synovial membranes of female patients with Osteoarthritis, Carhsp1 can regulate the stability of TNF -α mRNA, they might be associated with RA, no other proteins, such as Wars, Yars, Bzw2, Mcts1 and Eif4b were reported in RA." (PMID 35006449, 2021).
prostate carcinoma (1 paper, 2025). A carcinoma that arises from epithelial cells of the prostate gland. "Functionally, knockdown of CARHSP1 weakened the migration and invasion capacity of prostate cancer cells as detected by wound healing assays and transwell assays." (PMID 40055805, 2025). "On the other hand, both progression-free survival (PFS) and disease-free interval (DFI) of prostate cancer patients in the CARHSP1 high-expression group were significantly shorter than in the CARHSP1 low-expression group from the GSCA PCa database." (PMID 40055805, 2025). "However, there is an extremely limited understanding of the function of CARHSP1 as an RNA binding protein (RBP) in prostate cancer (PCa)." (PMID 40055805, 2025). "Combined with the results that high CARHSP1 levels correlate with higher T stages, these results uncovered that prostate cancer with high CARHSP1 levels may exhibit fast cell proliferation." (PMID 40055805, 2025). "Therefore, we then detected the role of CARHSP1 in TNF-α regulation in prostate cancer cells using RT-qPCR assay." (PMID 40055805, 2025). "Additionally, colony formation assays provided further confirmation of the enhancing effect of CARHSP1 on the growth of prostate cancer cells." (PMID 40055805, 2025). "However, the relationship between the CARHSP1 and PD-L1 in prostate cancer is still unknown." (PMID 40055805, 2025). "Firstly, correlation analysis in prostate cancer samples from TCGA cohort using TIMER and GEPIA database showed a positive correlation between mRNA levels of CARHSP1 and PD-L1." (PMID 40055805, 2025). "However, the result indicated that the effect of CARHSP1 knockdown on TNF-α mRNA was not consistent among different prostate cancer cell lines, which suggests that there are other factors in prostate cancer cells interfering with the regulation of CARHSP1 on TNF-α." (PMID 40055805, 2025).
vitiligo (1 paper, 2021). Generalized well circumscribed patches of leukoderma that are generally distributed over symmetric body locations and is due to autoimmune destruction of melanocytes. "In total, we propose the genes NUBPL, PHF11, SETDB2, RCBTB1, PTP4A1, and at a weaker replication level the genes LITAFD, CARHSP1 and OR2C1 as possible candidates for vitiligo-like depigmentation in grey horses." (PMID 34696794, 2021).
tumor (5 papers, 2020 to 2025). "The qPCR results indicated that the expression of protective genes (DCN and CARHSP1) gradually decreased in para-tumor, tumor, and pvtt tissues." (PMID 40051627, 2025). "A co-culture model of Jurkat cells and PCa cells was established to investigate the potential role of CARHSP1 in tumor immunity of PCa." (PMID 40055805, 2025). "The WB results showed that the expression of protective genes (DCN and CARHSP1) gradually decreased in para-tumor, tumor, and pvtt tissues." (PMID 40051627, 2025). "All results suggested that CARHSP1 knockdown attenuated the tumor proliferation of PCa in vitro and in vivo." (PMID 40055805, 2025). "Recent findings indicate that the involvement of CARHSP1 in the regulation of RNA stability plays a crucial role in tumor progression." (PMID 40055805, 2025). "Higher CARHSP1 mRNA expression in metastatic tumor tissues than in localized tumor tissues of PCa was evidenced by the analysis from four independent GEO expression datasets." (PMID 40055805, 2025). "The highlighted genes PHF11, SETDB2, CARHSP1 and LITAFD, are associated with the innate immune system, while the genes RCBTB1, LITAFD, NUBPL, PTP4A1, play a role in tumor suppression and metastasis." (PMID 34696794, 2021). "We hypothesized high levels of CARHSP1, KIAA0895, FBMIL1, and STRA6 may promote tumor progression." (PMID 34290231, 2021).
cancer (4 papers, 2022 to 2025). A tumor composed of atypical neoplastic, often pleomorphic cells that invade other tissues. "In the present study, we analyzed the expression of CARHSP1 in PCa and its association with cancer progression and patient prognosis; moreover, we detected function of CARHSP1 in cancer cells in vitro and in vivo." (PMID 40055805, 2025). "Knock down of CARHSP1 in 22Rv1 and PC-3 cells enhanced the T cell-mediated cancer cell killing with increased death PCa cells." (PMID 40055805, 2025). "Initially, bioinformatics analysis on the ULCAN website showed that CARHSP1 was highly expressed in several cancer types." (PMID 40055805, 2025). "Analysis of a recently published large-scale proteome dataset covering 375 cell lines of the Cancer Cell Line Encyclopedia for CSP-family expression showed that YBX1 and CARHSP1 are specifically overexpressed in hematologic malignancies." (PMID 34465866, 2022). "Previous studies have found that NF-κB might be upstream in the regulation of PD-L1 expression in many types of cancer, and GSEA results identified a positive correlation between CARHSP1 levels and “Hallmark_TNF-α_signaling Via NF-κB” in PCa." (PMID 40055805, 2025). "Moreover, it was observed that CARHSP1 increased the expression of MMP2 and MMP9 at the mRNA level and the protein level, which play vital roles in tissue remodeling, cancer progression, and metastasis." (PMID 40055805, 2025).
CARHSP1 also shares sentences with these, for which no sentence is quoted: glioblastoma (2 papers); hematologic malignancies (1).